EGFR (epidermal growth factor receptor)
Diseases named in the same sentence as EGFR in open-access papers (continued):
Sharing a sentence is not in itself a finding about the gene and the disease.
Burkitt lymphoma (5 papers, 2014 to 2023). A rare form of malignant mature B-cell non-Hodgkin lymphoma. "Our results revealing highly phosphorylated EGFR, PDGFRβ, ROR2, ERK1/2, or Hsp27 in all samples are also in accordance with previously published findings on Burkitt lymphoma." (PMID 32117783, 2019). "In this study, we investigated the interaction of EGFR and VEGF-A pathways in the context of two hematological in vitro models: THP1, a human monocytic leukemia, and Raji, a Burkitt’s lymphoma, cell lines." (PMID 27806094, 2016). "This study investigated the molecular mechanisms of interaction between EGFR and VEGFR signaling pathways in two hematological in vitro models: THP1 and Raji, a human monocytic leukemia and a Burkitt’s lymphoma cell lines; respectively." (PMID 27806094, 2016). "This study investigated the crosstalk between EGFR and VEGFR2 signaling in two hematological in vitro models: THP1, a human monocytic leukemia, and Raji, a Burkitt’s lymphoma, cell lines." (PMID 27806094, 2016). "In this study, EGFR and VEGFR2 were examined in two hematological in vitro models: THP1 and Raji, a human monocytic leukemia and a Burkitt’s lymphoma cell lines; respectively." (PMID 27806094, 2016).
cervical adenocarcinoma (5 papers, 2011 to 2025). An adenocarcinoma arising from the cervical epithelium. "Initial mechanistic studies on phosphorylation signaling and cholesterol depletion revealed that EGF-polystyrene nanoparticles exhibited cytotoxicity against human cervical adenocarcinoma HeLa cells via local enhancement of EGFR activity in membrane rafts." (PMID 41140511, 2025). "The percentage of cervical adenocarcinoma cases in which EGFR expression was detected varied from 19% to 67% in previous studies, and its overexpression was shown to be associated with poor prognosis." (PMID 28859123, 2017). "In conclusion, RTKs were strongly expressed in cervical adenocarcinoma, and patients who were double positive for EGFR and HER2 showed significantly shorter RFS." (PMID 28859123, 2017). "In consistence, c-ABL has been identified as a synthetic lethal partner of EGFR in an unbiased screening using the A431 cervical adenocarcinoma cells." (PMID 25883211, 2015). "Our results suggest that EGFR and HER2 are potential therapeutic targets and that their co-expression of them is a prognostic factor for cervical adenocarcinoma." (PMID 28859123, 2017). "Our results suggest that EGFR and HER2 are potential therapeutic targets and that their co-expression is a prognostic factor for cervical adenocarcinoma." (PMID 28859123, 2017). "Recently, the expression of receptor tyrosine kinases (RTKs), EGFR, HER2 and c-Met, has been considered in connection with uterine cervix adenocarcinoma." (PMID 28859123, 2017). "This is the first study to evaluate the impact of co-expression of RTKs (EGFR, HER2, and c-Met) on relapse-free survival and overall survival of patients with cervical adenocarcinoma." (PMID 28859123, 2017). "Although these RTKs are known to play a key role in oncogenic transformation, carcinogenesis and tumor invasiveness, there is little information about the relationships between EGFR, HER2 and c-Met in cervical adenocarcinoma." (PMID 28859123, 2017). "To evaluate the significance of the expression of multiple RTKs in uterine cervical cancers, we examined the expression profile of RTKs (EGFR, HER2 and c-Met) and the correlation of their expression with clinicopathological features and prognosis of patients with cervical adenocarcinomas." (PMID 28859123, 2017). "In particular, EGFR-targeting agents (e.g., cetuximab and panitumumab) or HER2-targeting agents (e.g., trastuzumab) may have efficacy in cervical adenocarcinomas." (PMID 28859123, 2017). "Fluorescence staining was observed after incubation of the EGFR-expressing human cervix adenocarcinoma cell line HeLa with αEGFRN7, while no binding was detected for αGFPN7." (PMID 27345490, 2016).
cholestasis (5 papers, 2016 to 2025). Impairment of the bile flow caused by obstruction within the liver, or outside the liver in the bile duct system. "Of note, the high expression of AREG upon cholestasis injury liver, caused by intrahepatic accumulation of BAs that promotes SRC and ADAM17 activation, induces activation of EGFR." (PMID 39966897, 2025). "Further studies are required to better characterize the role of ADAM17 within the liver microenvironment and inflammatory milieu as it pertains to cholangiocyte response, bile duct injury, TGFα, EGFR signaling and overall cholestasis." (PMID 35095853, 2021). "We have shown that activated STAT3 and the closely related STAT5 protein protect from cholestasis-induced liver injury by partly overlapping molecular mechanisms that include regulation of EGFR." (PMID 27568040, 2017). "Conversely, other studies suggest an opposite EGFR function in cholestasis liver injury, demonstrating that the deletion of the catalytic domain of EGFR can be beneficial, reducing collagen gene expression, promoting anti-inflammatory responses, and increasing M2 macrophages that suppress fibrosis." (PMID 39966897, 2025). "Taken together, our findings provide direct evidence that excessive CDCA can serve as endogenous danger signal to activate NLRP3 inflammasome by TGR5/EGFR signaling and promoting ATP release, therefore, identifying a new mechanism by which inflammation is initiated during cholestasis." (PMID 27924062, 2016).
crescentic glomerulonephritis (5 papers, 2013 to 2024). A histopathologic term for a pattern of diseases characterized by extensive crescent formation in the glomeruli; patients present clinically with rapid deterioration of renal function, and possible progression to end-stage renal failure within weeks or months. "Taken together, glucocorticoids exert therapeutic effect on anti-GBM crescentic glomerulonephritis through inhibiting podocyte EGFR/STAT3 signaling and the downstream pathway that leads to PEC proliferation and crescent formation." (PMID 35223886, 2022). "It appears that the development of crescentic glomerulonephritis may also follow the sequence of EGFR/STAT3/Notch activation, secreted factors expression in podocytes, and Notch activation and cellular proliferation in PECs." (PMID 35223886, 2022). "These authors also found a strong upregulation of renal AREG expression in human crescentic glomerulonephritis and thereby suggesting that AREG/EGFR axis might represent a new therapeutic target for patients with acute glomerulonephritis." (PMID 39234105, 2024). "Glucocorticoids may suppress expression of EGFR ligands and upregulate expression of Gene 33, thereby preventing activation of EGFR and downstream pathway that leads to PEC activation and proliferation, and eventually alleviating anti-GBM crescentic glomerulonephritis." (PMID 35223886, 2022). "However, although EGFR-TKI alleviated proteinuria and kidney injury in crescentic glomerulonephritis, in clinical trials, the combination of VEGFR2 monoclonal antibody ramucirumab and EGFR inhibitor erlotinib resulted in the increased incidence of proteinuria compared to ramucirumab alone." (PMID 33921219, 2021).
diabetic retinopathy (5 papers, 2021 to 2025). "It was also confirmed that overexpression of hsa-miR-199a-3p inhibits the proliferation, migration, and invasion of endothelial cells and retinal pericytes of diabetic retinopathy rats through regulating FGF7 via the EGFR/PI3K/AKT pathway." (PMID 36859746, 2023). "The previous studies have indicated that EGFR inhibitors played the important role in attenuating inflammatory infiltration and angiogenesis in mice with diabetic retinopathy." (PMID 35024051, 2022). "Studies and experiments have certified that regulating the EGFR pathway also could inhibit the proliferation, migration, and invasion of endothelial cells and retinal pericytes of diabetic retinopathy rats." (PMID 35024051, 2022).
dilated cardiomyopathy (5 papers, 2013 to 2023). Cardiomyopathy which is characterized by dilation and contractile dysfunction of the left and right ventricles. "To validate our findings in patients with AC, we assessed EGFR protein levels in lysates obtained from the atrial appendage of hearts from patients with AC and observed increased EGFR protein levels compared with dilated cardiomyopathy (DCM) hearts." (PMID 36795511, 2023). "Several biological pathways were found to have significant associations with SBP: dilated cardiomyopathy (DCM), hormone ligand‐binding receptors, EGFR smrte pathway, and tyrosine metabolism." (PMID 34586716, 2021). "As inhibition of EGFR contributes to dilated cardiomyopathy, β1AR signaling via βarr2 appears to be protective rather than deleterious for the heart and βarr2-dependent EGFR transactivation might exert a cardio-protective effect." (PMID 24351844, 2013).
endotoxemia (5 papers, 2017 to 2023). "We describe a novel approach by which EGFR is involved in endotoxemia by regulating the M1/M2 phenotype transformation of macrophages through cell metabolism." (PMID 36344490, 2022). "Probiotics also prevent and mitigate alcohol-induced disruption of colonic epithelial tight junctions, endotoxemia, and liver damage by an epidermal growth factor receptor- (EGFR-) dependent mechanism." (PMID 31263495, 2019). "In LPS-induced endotoxemia, Erlotinib pretreatment could maintain mitochondrial membrane potential (ΔΨm) levels and ATP content, suggesting that EGFR is involved in energy metabolism during macrophage activation." (PMID 36344490, 2022). "In addition, phosphorylation of Rab7a promotes LPS-induced EGFR membrane expression, activated macrophages, and promotes lung tissue injury in mice with endotoxemia." (PMID 36344490, 2022). "Inhibition of EGFR may have therapeutic potential for AKI during endotoxemia." (PMID 29207668, 2017). "Our lab further demonstrated that EGFR and TLR4 co-regulate macrophage activation in endotoxemia and EGFR phosphorylation is necessary to increase TLR4 cell surface expression and signal transduction." (PMID 36344490, 2022). "We found that Rab10 active-site mutant altered the expression of cell surface EGFR in RAW264.7 macrophages during endotoxemia but did not affect total protein levels of EGFR expression." (PMID 36344490, 2022).
Familial adenomatous polyposis (5 papers, 2017 to 2025). Familial adenomatous polyposis (FAP) is characterized by the development of hundreds to thousands of adenomas in the rectum and colon during the second decade of life. "We present the first case of a male patient with an epidermal growth factor receptor (EGFR) 19del mutation who was diagnosed with intra-abdominal aggressive fibromatosis and familial adenomatous polyposis." (PMID 40727479, 2025). "Here, we used patient-derived organoids (PDOs) derived from a familial adenomatous polyposis (FAP) patient to analyze the response to chemotherapeutic agents targeting EGFR, BRAF and MEK." (PMID 33060766, 2020). "Furthermore, the EGFR inhibitor erlotinib proved active when combined with the NSAID sulindac in a polyp trial with familial adenomatous polyposis (FAP) patients." (PMID 37169023, 2023). "More recently, dual targeted antibodies targeting T cells and cancer-specific cell surface antigens such as epidermal growth factor receptor (EGFR), FR-a, familial adenomatous polyposis (FAP) and CD44v6, have demonstrated promising preclinical results." (PMID 32600470, 2020).
gliomatosis cerebri (5 papers, 2005 to 2024). A diffuse glial tumor which infiltrates the brain extensively, involving more than two lobes. "In Case 2 with H3K27M-mutated DMG (and BRAFV600E and SMARCB1 alterations), and Case 3 with gliomatosis cerebri (EGFR overexpression and CDKN2A deletion) in reduced clinical condition, local re-irradiation and targeted therapy (with or without chemotherapy and/or immunotherapy) were proposed." (PMID 36720762, 2023). "However, there was an 18–22% incidence of gliomatosis cerebri in all EGFR expression categories in the less than GTR patient group compared to only 3–5% incidence in those patient who underwent GTR." (PMID 16236164, 2005).
glomerular disease (5 papers, 2012 to 2025). "Kidney EGFR expression together with reported cases of glomerular diseases in the context of anti-EGFR drug administration raise concerns about the renal safety profile of these drugs." (PMID 34885014, 2021). "Signaling through epidermal growth factor receptor (EGFR) in podocytes mediates development of many glomerular disease processes." (PMID 29549365, 2018).
helminth infection (5 papers, 2017 to 2025). "This indicated that Lingo2 deficiency protected against helminth infection, at least in part, due to EGFR activity." (PMID 31562318, 2019). "EGFR deficiency in T cells increases susceptibility to helminth infection." (PMID 39966897, 2025). "EGFR expression on Th2 cells is critical for resistance during GI helminth infection and a signalling complex between EGFR and ST2 can activate Th2 cells to secrete IL-13 in an antigen-dependent manner upon IL-33 exposure." (PMID 32636457, 2020). "After gastrointestinal helminth infection, activated CD4+ helper T cells in mice show increased EGFR expression, induced by cytokine-dependent signaling." (PMID 39966897, 2025). "Moreover, during helminth infection, ST2L forms an active signaling complex with the epidermal growth factor receptor (EGFR) on Th2 cells, following amphiregulin-induced phosphorylation and activation of EGFR." (PMID 35011670, 2021).
hepatoblastoma (5 papers, 2019 to 2024). Hepatoblastoma (HB) is a malignant hepatic tumor and is the most common pediatric liver cancer. "In conclusion, our study revealed EGFR as a novel host factor for HEV’s entry process in hepatoblastoma-cell culture systems and also ex vivo in PHHs, underlining the relevance of this particular factor." (PMID 36745934, 2023). "In hepatoblastoma, the loss of ASAP1 and EGFR expression was observed in histologically poor differentiated cases, and this trend was more pronounced in metastatic and unresectable cases." (PMID 37762658, 2023). "Furthermore, we found that FGFR and EGFR inhibitors were specific for the respective hepatoblastoma subtypes compared to the reference cohort." (PMID 39567475, 2024). "Intriguingly, embryonal and fetal tumor organoids are sensitive to FGFR and EGFR inhibitors, respectively, indicating a dependency on EGF/FGF signaling in hepatoblastoma tumorigenesis." (PMID 39567475, 2024).
Hydrocephalus (5 papers, 2016 to 2025). Hydrocephalus is an active distension of the ventricular system of the brain resulting from inadequate passage of CSF from its point of production within the cerebral ventricles to its point of absorption into the systemic circulation. "Recently, we discovered that a heparin binding epidermal growth factor like growth factor (HB-EGF)—a class of EGF receptor (EGFR) family ligands—contributes to the development of hydrocephalus with subarachnoid hemorrhage through activation of VEGF signaling." (PMID 29342116, 2018). "Favorable prognostic factors included a good KPS, effective primary cancer control, absence of IICP at hydrocephalus diagnosis, and active treatments such as EGFR-TKI therapy." (PMID 40106020, 2025).
intrauterine growth restriction (5 papers, 2011 to 2023). "EGFR is active during the window of implantation, and the impaired activation of such has been linked to many birth defects, such as intrauterine growth restriction and low birth weight." (PMID 37047784, 2023). "In human trophoblast, EGF has been shown to stimulate differentiation to SynT in vitro and decreased EGFR phosphorylation is associated with intrauterine growth restriction." (PMID 33141023, 2020). "Notably, the gene with the most linked enhancers, encoding epidermal growth factor receptor (EGFR), is important for trophoblast function and is altered in cases of intrauterine growth restriction." (PMID 37694817, 2023). "Reduced expression of EGFR is observed in many pregnancy-related complications including preeclampsia (PE), intrauterine growth restriction (IUGR), and recurrent spontaneous abortion." (PMID 34620174, 2021). "Nevertheless, growth factors such as EGF are believed to be intimately involved with the control of trophoblast physiology, and abnormal levels of EGFR have been reported in the placenta from pregnancies complicated by intrauterine growth restriction (IUGR), preeclampsia, and diabetes mellitus." (PMID 21876698, 2011).
leiomyosarcoma (5 papers, 2012 to 2023). An uncommon, aggressive malignant smooth muscle neoplasm, usually occurring in post-menopausal women. "The aim of the current study was to evaluate the phosphorylation of epithelial growth factor-receptor (EGFR) in normal myometrium, uterine myomas and uterine leiomyosarcomas." (PMID 23449029, 2013). "Our findings further support these results and highlight a role for EGFR and especially for the activation by phosphorylation of Y845, as far as uterine leiomyosarcoma is concerned." (PMID 23449029, 2013). "The aim of this study was to evaluate differences in the EGFR activation by phosphorylation in myomas and leiomyosarcomas." (PMID 23449029, 2013). "Interestingly, in the transformed cells of human leiomyosarcoma SK-UT-1B originated from placenta and uterus, EGFR protein level is several fold lower than in all other MSC and transformed cell lines used." (PMID 37686213, 2023).
liver failure (5 papers, 2020 to 2026). A liver disease characterized by the liver losing or has lost all of its function. "We have reported an exon 19 EGFR-mutated young female, who developed a systemic continuous fever, intestinal lung pneumonitis, and severe liver failure with Stevens–Johnson syndrome after the sequential administration of ICIs and TKIs." (PMID 37628803, 2023). "Regarding Hepatic insufficiency, Gefitinib exhibited higher incidence rates than other EGFR-TKIs and chemotherapy, with an AST increased incidence rate of 24% and alanine ALT increased at 23%." (PMID 40135231, 2025). "EGFR has been reported to prevent hepatocyte apoptosis and liver failure." (PMID 39187547, 2024).
male infertility (5 papers, 2020 to 2025). The inability of the male to effect fertilization of an ovum after a specified period of unprotected intercourse. "EGFR, the signalling dysfunction of which was associated with human male infertility, might be coregulated by FXR1, FXR2, and HNRNPA1 (all of these three bind EGFR from CLIP experiments), G3BP2, G3BP1, FMR1, and SRSF7." (PMID 32316190, 2020). "Growth factor receptors, including EGFR, FGFR, and IGF1R, regulate essential testicular processes, sperm development and maturation, and their dysregulation has been linked to male infertility and testicular dysfunction." (PMID 40331996, 2025).